GAST (gastrin)
Diseases named in the same sentence as GAST in open-access papers (continued):
Sharing a sentence is not in itself a finding about the gene and the disease.
colon carcinoma (continued). "Finally, NCI-H716 cells have features of endocrine differentiation, ccurring in less than 1% of colon cancer, including expression of receptors for serotonin, gastrin and somatostatin, and expression of cytoplasmic core granules." (PMID 24968263, 2014). "Furthermore, ANXA2 mediates the effects of gastrin/PG peptides that stimulate the growth of autocrine and exogenous gastrin and PG peptides on intestinal epithelial and colon cancer cells." (PMID 24591759, 2014). "Our hypothesis was that gastrin peptides locally produced in colonic tumors can influence the function of infiltrated macrophages and, in this way, modulate the immune response to disease." (PMID 24901518, 2014). "We hypothesized that progastrin could be responsible for the effects observed on macrophage phenotype, because colon cancer cells lack the enzymes necessary for complete gastrin maturation." (PMID 24901518, 2014). "Recently, ANXA2 is identified as a novel receptor for gastrin and progastrin (PG) peptides, which mediate the growth stimulatory effects of autocrine and exogenous gastrin and PG peptides on intestinal epithelial and colon cancer cells." (PMID 24591759, 2014). "Repression of the gastrin gene in human colon cancer cells by antisense gastrin RNA yields a significant growth inhibition of these cells, suggesting that gastrin expression may be required for colon tumour progression." (PMID 15798764, 2005). "Furthermore, a positive temporal relationship has been observed between hyper-gastrinaemia and increased incidence of colon cancer with 8.9% of colon cancer being shown to be attributable to elevated gastrin levels, indicating a sub-group of patients exhibiting increased sensitivity." (PMID 12189558, 2002). "Moreover, in a clinical study of open surgery for colon cancer, patients undergoing intravenous anesthesia involving dexmedetomidine had a quicker recovery of gastrointestinal motility, and the levels of prokinetic gastrointestinal hormones such as motilin and gastrin in the plasma increased." (PMID 39758778, 2024). "The orthotopic colon cancer model of CMT93 cells with long-term PPI administration showed enhanced tumor growth and liver metastasis due to gastrin and YAP activation, as indicated by gastrin receptor knockdown and treatment with a YAP inhibitor." (PMID 32485921, 2020). "To study the role of CacyBP/SIP in proliferation of colon cancer cells, we examined the effect of CacyBP/SIP knockdown on the cell proliferation under either basal condition or treatment with gastrin, a hormone known to trigger colon cancer." (PMID 28196083, 2017). "Lastly, there is a mounting scientific debate concerning the role of gastrin precursors, such as gastrin-gly, which seem to upregulate proangiogenic factors, like VEGF in colon cancer cells." (PMID 22719803, 2012). "We have shown that a gastrin transcript expressed in a panel of GI cancer cell lines contains an IRES that has basal activity in both pancreatic and colon cancer cells." (PMID 18392051, 2008). "Tumour growth factor-alpha and epidermal growth factor (EGF) are involved in upregulation of gastrin expression in a number of colon cancer cell lines through binding to an established EGF response element, gERE, within the gastrin promoter." (PMID 17262081, 2007). "This study examined the expression level, subcellular localization, and binding activity of CacyBP/SIP in human colon cancer cells in the presence and absence of the hormone gastrin." (PMID 28196083, 2017). "Gastrin‐SiO2 microspheres (20 mg kg−1 day−1, 80 μL/10 g), administered by gavage (10–20 s), did not affect the mRNA expression of inflammatory factors (TNFα, MCP‐1, MCP‐2, IL‐1β, and IL‐6) in the intestine and colon cancer promoting markers in the serum (CEA, CA199, and PSA)." (PMID 39950948, 2025). "Furthermore, through fluorescence activated cell sorting (FACS), we found that progastrin binds to the GPR56 (+) colon cancer cell surface, while amidated gastrin (G-17) did not." (PMID 28380450, 2017).
colon carcinoma (continued). "Several publications have shown that the receptor specific for the mature form of gastrin, the CCK-2 receptor, is not involved in the PG effect on fibroblasts or colon cancer cells." (PMID 24209454, 2013).
gastroesophageal reflux disease (27 papers, 2012 to 2025). A chronic disorder characterized by reflux of the gastric and/or duodenal contents into the distal esophagus. "The secretin-provocative test is most useful in patients with recurrent ulcer disease, severe reflux esophagitis, and chronic diarrhea associated with modest elevations of serum gastrin levels." (PMID 25698559, 2015). "The underlying mechanisms, other than gastrin regulation, for improving temporal gastroesophageal reflux-related symptoms such as heartburn, remain unclear." (PMID 38674920, 2024). "Akt is activated in oesophageal Barrett’s cells by acid-reflux and by hormones such as gastrin and glycine-extended gastrin as well as leptin." (PMID 33582946, 2021). "This increase of the gastrin concentration in fasting patients overlaps with hypergastrinaemia seen in fasting patients with idiopathic peptic disease or gastro-oesophageal reflux disease." (PMID 24213225, 2012). "Gastroesophageal reflux was reported in three pregnancies; two patients had normal serum gastrin levels, while gastrin status was unknown in the third." (PMID 40710389, 2025). "ZES is a group of symptoms comprising severe peptic ulcer disease, gastroesophageal reflux disease (GERD), and chronic diarrhea caused by a gastrin-secreting tumor of the duodenum or pancreas (gastrinoma triangle) that results in increased stimulation of the acid-secreting cells of the stomach." (PMID 33920345, 2021). "This low gastrin secretion may explain why reflux esophagitis is less likely to occur after H. pylori eradication in cases with duodenal ulcers." (PMID 33917861, 2021). "The role of gastrin in gastric carcinogenesis implies caution in the long-term treatment with inhibitors of gastric acid secretion inducing secondary hypergastrinemia, in a common disease like gastroesophageal reflux disease." (PMID 28144230, 2017). "Consequently, glutamate might indirectly affect gastric acid production by modulating the release of gastrin, thereby influencing the progression and symptoms of gastroesophageal reflux disease." (PMID 40103821, 2025). "Its cells produce excessive amounts of gastrin, leading to the fundic parietal cell hyperplasia and a significant increase in basal gastric acid secretion and, as a result, peptic ulcer disease, advanced gastroesophageal reflux, and chronic diarrhea, which is called ZES." (PMID 37008936, 2023). "Therefore, although most of the temporal gastroesophageal reflux-related symptoms in the participants in this study were seemingly not related to high serum gastrin levels, in some participants, a decrease in serum gastrin concentration possibly reduced their stomach complications." (PMID 38674920, 2024). "This syndrome is characterized as a group of symptoms occurring due to an increase in gastric acid secretion, including peptic ulcer disease, gastroesophageal reflux disease (GERD), and gastrin-secreting tumor of the duodenum." (PMID 37090344, 2023). "Gastrin is known to increase the contractile activity of the lower esophageal sphincter (LES), thus reducing the incidence of gastro-esophageal reflux." (PMID 30011784, 2018). "Previous studies have found higher gastrin release following PPI therapy in females compared with males, and sex differences have also been demonstrated in pharmacokinetic parameters and dose requirements for acid reflux." (PMID 38139847, 2023). "The last finding also demonstrated that EDs containing caffeine can stimulate gastrin and gastric acid secretion and may reduce the competence of the lower esophageal sphincter, which eventually leads to gastroesophageal reflux disease (GERD)." (PMID 34444666, 2021). "For example, gastrin has low utility as a biomarker since secretion is elevated in low acid conditions like CAG, during persistent Helicobacter pylori infection, or through use of proton pump inhibitors (PPIs) for e.g., gastroesophageal reflux disease (GERD)." (PMID 32703157, 2020).
gastroesophageal reflux disease (continued). "An increase in gastrin and a decrease in somatostatin in all IBS subtypes may result in high levels of gastric acid secretion, which may explain the frequent occurrence of dyspepsia and gastroesophageal reflux in IBS patients." (PMID 37296188, 2023).
neuroendocrine tumors (26 papers, 2009 to 2025). "In contrast, AIG causes tumorigenesis of neuroendocrine tumor possibly by elevated gastrin levels due to the destruction of parietal cells." (PMID 37962678, 2024). "The principal mechanism underlying gastrin’s involvement in neuroendocrine tumor development is its stimulatory effect on the growth of enterochromaffin-like cells within the stomach." (PMID 37504250, 2023). "Zollinger–Ellison syndrome (ZES) is caused by ectopic secretion of gastrin from a neuroendocrine tumor resulting in severe acid hypersecretion requiring life-long antisecretory treatment with PPIs, which are the drugs of choice." (PMID 31623145, 2019). "However, PAPPA2 has not been associated previously with gastrointestinal disease, gastrin signaling, or neuroendocrine tumor development." (PMID 32004755, 2020). "ECL cells are the key target cells of gastrin in the oxyntic mucosa, and are associated with the expression of cholecystokinin-2 (CCK-2) receptors and the formation of neuroendocrine tumors (NETs)." (PMID 35804824, 2022). "We further explore the molecular biology of gastrin in GI malignancies, with particular emphasis on the regulation of gastrin in neuroendocrine neoplasms." (PMID 35330921, 2022). "Core tips: ZES is characterized by significant hypergastrinemia derived from a gastrin-secreting neuroendocrine tumor." (PMID 34945075, 2021). "It is characterized pathophysiologically by significant hypergastrinemia derived from a gastrin-secreting neuroendocrine tumor with a primary location in the pancreas or duodenum (gastrinoma triangle)." (PMID 34945075, 2021). "Anlauf and his co-authors found that 13/28 (46.4%) duodenal gastrin-producing neuroendocrine tumors and 2/5 (40%) somatostatin-secreting neuroendocrine tumors revealed LOH of 11q13 from six patients with Zollinger–Ellison syndrome and MEN1." (PMID 32126984, 2020). "Type 4 gastric carcinoids are sporadic in nature, gastrin-independent, poorly differentiated neuroendocrine tumors, comprise 6–8% of all gastric carcinoids, and metastasize in 50–100%." (PMID 31623145, 2019). "A metastasising somatostatinoma was histologically proven and evidence of a concomitant gastrin-producing neuroendocrine tumour was found." (PMID 29568575, 2015). "If this is a unique species-specific feature of canine GB NEN, gastrin expression could be targeted therapeutically to limit clinical signs and reduce tumor burden, as described in other gastrin-secreting canine neuroendocrine tumors." (PMID 41150129, 2025). "Zollinger–Ellison syndrome is characterized by recurrent peptic ulcers and diarrhea that result from gastrin-secreting neuroendocrine tumors of the gastrointestinal tract; nevertheless, severe hypergastrinemia may also have alternative pathogenetic explanations." (PMID 23432909, 2013). "Although serum gastrin levels were higher in those treated with vonoprazan, there were no reports of malignant alterations or neuroendocrine tumors in either group." (PMID 40937184, 2025).
ulcer (25 papers, 2009 to 2025). "The reduction in gastrin production and its impact on the stomach lowers the risk of peptic ulcers and aids in the healing of those who already have ulcers." (PMID 41028410, 2025). "In this study, we found that PPI or PCAB usage for ulcers caused by ESD increased serum gastrin and PG levels." (PMID 35126509, 2022). "On the other hand, Ito and Mason hypothesized that in a remnant stomach with an intact vagal nerve supply, if the gastric antrum remained sufficiently bathed in gastric acid, it could deactivate its antral gastrin secretory response, thus decreasing the risk for ulcers." (PMID 40351907, 2025). "Cortisol and gastrin levels in the ulcer group exhibited a remarkable increase of approximately 671% and 431%, respectively, compared to the control group." (PMID 40563542, 2025). "Concurrent Helicobacter pylori infection at ulcer sites elevates gastrin release, gastric acid secretion, and pepsinogen activity, collectively disrupting the anastomotic healing microenvironment." (PMID 40956011, 2025). "Treatment with OMP led to a 49% decrease in cortisol levels and a 36% reduction in gastrin levels in the ulcer group, whereas OMP-NS further lowered cortisol levels by roughly 75% and gastrin levels by around 61%." (PMID 40563542, 2025). "Specifically, these polysaccharidesmodulated the volume of gastric secretions (gastric fluid, gastricacid, pepsin, and gastrin) in rats with ulcers." (PMID 40063730, 2025). "The pantoprazole group showed a significantly increased serum gastrin level in comparison with the ulcer group." (PMID 38457071, 2024). "Serum gastrin levels were markedly higher in the ulcer group compared to the control group (P < 0.001)." (PMID 38457071, 2024). "The administration of pantoprazole resulted in a significant increase in serum gastrin levels relative to the ulcer group (p = 0.002)." (PMID 38457071, 2024). "In this study, a peptic ulcer model in Sprague‒Dawley (SD) rats was induced by aspirin, and the effects of omeprazole (Ome) at different dosing frequencies on ulcer healing and gastrin expression were observed." (PMID 38811868, 2024). "We found a significantly increased serum gastrin level and gastric acid production, confirmed by low gastric pH in the ulcer group." (PMID 38457071, 2024). "The limitation of this study is that the effects of omeprazole once every other day on the prevention of ulcers, gastrin levels, and cell proliferation were observed over a relatively short period." (PMID 38811868, 2024). "Estrogen can prevent ulcers by inhibiting the synthesis and release of gastrin and reducing the secretion of gastric acid." (PMID 35144540, 2022). "I/R leads to an excessive production of reactive oxygen species and gastrin reducing simultaneously the local microcirculation provoking acute erosions and ulcer in gastric mucosa." (PMID 34744702, 2021). "Gastrin stimulates the production of gastric acid by parietal cells and, in H. pylori colonization responses that increase gastrin, the increase in acid can contribute to the erosion of the mucosa and therefore ulcer formation." (PMID 22389852, 2011). "Estrogen may play a protective role against ulcers by inhibiting both the synthesis and release of gastrin, as well as reducing gastric acid secretion." (PMID 40644423, 2025). "Polaprezinc has the potential to positively impact the process of ulcer healing via several mechanisms in rat models, including the mediation of zinc(2+) to enhance gastric microcirculation, exhibit antisecretory activity, and stimulate gastrin release." (PMID 37836377, 2023). "TNF-α plays a major role in indomethacin-induced gastric mucosal injury, as it reduces blood flow to the gastric mucosa and increases the gene expression of gastrin and vascular endothelial growth factor in the gastric mucosa, and thus hinders the ulcer healing process." (PMID 33530540, 2021).
ulcer (continued). "The presence ofhypertrophic and heterotopic gastric mucosa isproposed to result from increased gastrin levelsand may contribute to the increased incidence ofpostbulbar ulcers in thesepatients." (PMID 19587828, 2009). "Moreover, calcium influx across or into the cell membrane is a primary factor associated with the stimulation of gastrin, and patients with duodenal ulcers are more sensitive than those without ulcers." (PMID 31382574, 2019). "Since the ulcer risk genotype of TLR4 associated with high serum gastrin but not with gastric inflammation, we suggest that the role of TLR4 in the regulation of gastric secretion is more important in mediating the ulcer risk than its direct proinflammatory effects." (PMID 26161647, 2015). "The ulcer group revealed a significant increase in MDA, gastrin, NLRP3, and GSDMD and a decrease in gastric pH and GSH compared to the control group." (PMID 38457071, 2024). "Epithelial cell proliferation during ulcer healing is inhibited by CCK2R blockade and stimulated by omeprazole and exogenous gastrin; however, CCK2R expression in this setting is typically transient and quickly downregulated." (PMID 27448962, 2017). "In addition, a direct comparison between the ulcer + OMP and ulcer + OMP-NS groups revealed that the OMP-NS group exhibited significantly lower cortisol and gastrin levels than the OMP group (p < 0.0001), indicating a superior efficacy in modulating stress and gastric hormone responses." (PMID 40563542, 2025). "Thus TLR4 activation and its effects on gastrin and acid secretion might also have a role in the pathogenesis of NSAID ulcers." (PMID 26161647, 2015).